MMP9 (matrix metallopeptidase 9)
Diseases named in the same sentence as MMP9 in open-access papers (continued):
Sharing a sentence is not in itself a finding about the gene and the disease.
Obesity (continued). "The rare allele of PPARG SNP rs3856806 has been linked with not only coronary artery disease progression, but also with pro-inflammatory cytokines (MMP9 and TNFα), plasma homocysteine levels, and obesity." (PMID 20426853, 2010). "Since MMP9 is upregulated in hypertrophic adipocytes, such elevation may be limited in mild obesity." (PMID 40806842, 2025). "Chronic low-grade inflammation is a key driver of metabolic dysfunction in obesity, and targeting MMP-9 may help reduce tissue remodeling and systemic inflammation." (PMID 40565127, 2025). "Whether changes in fibrosis-related gene expressions were associated with obesity or chronic light exposure, TRF intervention effectively reduced these, except for the Mmp9 gene." (PMID 39519077, 2024). "This study aims to determine plasma concentrations of MMP-2 and MMP-9, as well as clinical and laboratory parameters related to obesity throughout the follow-up period, to investigate the associations between these markers and the effects of weight loss in patients undergoing bariatric surgery." (PMID 39766340, 2024). "In addition, the MMP9/TIMP1 ratio has been associated with endothelial dysfunction, which is frequent in obesity-related cardiovascular disorders." (PMID 39594522, 2024). "Furthermore, mRNA levels of the N6-methyladenosine (m6A) demethylase, fat mass and obesity-associated protein (FTO), and the hydrolase matrix metalloproteinase-9 (MMP9), also increased in the mPFC." (PMID 38672038, 2024). "To further explicitly distinguish the specific impact of OSAS and obesity on systemic immunological balances, we analyzed plasma levels of adiponectin, leptin, lipocalin and metalloproteinase 9 (MMP-9) from normal weight OSAS patients and patients with obesity without OSAS using ELISA measurements." (PMID 38172514, 2024). "MMP9 contributes considerably to obesity by regulating extracellular matrix remodeling." (PMID 39594522, 2024). "Furthermore, we measured MMP-9 levels that play an important role in obesity-mediated adipose tissue remodeling." (PMID 38362105, 2024). "In addition, OSAS and obesity related plasma levels of adiponectin, leptin, lipocalin, and matrix metallopeptidase 9 (MMP-9) were correlated with monocyte subset measurements and clinical characteristics to explicitly distinguish these two conditions." (PMID 38172514, 2024). "Based on our findings, it can be concluded that these four genes (MNDA, TNC, CHIT1, and MMP9) may have important biological roles in preventing and treating obesity and PTC." (PMID 37671970, 2023). "Clinical trials in PWS has been used the anti-obesity medication liraglutide and the hormone oxytocin as studies suggest these medications may reduce MMP-9 and improve CVD." (PMID 37430349, 2023). "In conclusion, these four genes (MNDA, TNC, CHIT1, MMP9) may serve as a link between obesity and PTC and should be further examined in subsequent analyses." (PMID 37671970, 2023). "Increased plasma concentrations of MMP-2 and MMP-9 were found in patients with obesity and T2D." (PMID 37446346, 2023). "In this study, we constructed a co-expression network between obesity and PTC and identified four common hub genes (MNDA, TNC, CHIT1, MMP9) and two common TFs (ELF4, STAT3), which might provide new diagnostic and therapeutic strategies for obesity-related PTC." (PMID 37671970, 2023). "Of note, MMP-7 and MMP-9 were highly upregulated by 42.5 and 16.3 fold in obesity, respectively." (PMID 35958557, 2022). "Moreover, leptin, a possible key mediator linking obesity to OA, modulates the degradative functions of the chondrocytes through the upregulation of MMP9 and −13." (PMID 35329213, 2022). "MMP-9 and obesity further promote the invasive ability of hepatocellular carcinoma cells." (PMID 35873545, 2022). "Overall, inflammation may play the role of a bridge between obesity and Alzheimer’s disease, and the four hub genes above (MMP9, PECAM1, C3AR1, and IL1R1) are critical to this." (PMID 36568118, 2022).
Obesity (continued). "The present study demonstrated the modifying effect of obesity on the association of MMP gene polymorphisms with BC: rs17576, and rs2250889 MMP9 were BC protective factors in obese women; rs243865 MMP2, and rs3787268 MMP9 determined BC susceptibility in non-obese women." (PMID 36289879, 2022). "MMP-9 is secreted from pericytes, fibroblasts and macrophages and may be reflective of increased inflammatory macrophage presence in scWAT in obesity." (PMID 35958557, 2022). "Other described released mediators by neutrophils on obesity were IL‐8, MMP‐9 or MPO." (PMID 35818731, 2022). "Indeed, promotors of several obesity-related genes, such as fibrosis-related gene MMP9, remained differentially methylated and their expression was still perturbed after 6 months of diet reversion." (PMID 33777102, 2021). "Indeed, increased levels of TNF-α, IL-6, MMP-9, and VEGF have been extensively documented in obesity and found to be associated with metabolic inflammation, hyperglycemia, insulin resistance and progression to type-2 diabetes or metabolic syndrome." (PMID 34230580, 2021). "Other obesity‐associated factors such as leptin might have been better proxy measures of maternal obesity, since leptin can inhibit inflammation‐mediated MMP2 and MMP9 activation at least at term of pregnancy." (PMID 32614494, 2020). "MMP9, which encodes metalloproteinase 9 and ILTRN, was increased by sevenfold in obesity." (PMID 32826922, 2020). "Our data indicate that an increase in serum MMP-9 may precede the development of obesity and disturbances of glucose tolerance and that the offspring of type 2 diabetic patients are at elevated risk for CVD." (PMID 30302090, 2018). "Also, other systemic conditions such as obesity and metabolic syndrome elevate serum MMP-9 concentrations." (PMID 29349668, 2018). "Together, these data demonstrate that obesity is responsible for MMP3-induced MMP9 activation in tumor patients and this process may be mediated by exosomes." (PMID 29137230, 2017). "In summary, our results conclude that infiltrating pre-adipocytes could promote PCa metastasis via modulation of the miR-301a/AR/TGF-β1/Smad/MMP9 signaling, which might explain the link of potential obesity influences on the PCa progression." (PMID 25940439, 2015). "Descriptive statistics of all study participant saliva samples tested for Bone Panel (osteoprotegrin (OPG), leptin, parathyroid hormone (PTH) and insulin), Matrix Metalloproteinase Panel (MMP-2, MMP-8, MMP-9) and Obesity Panel (adiponectin and C-reactive protein (CRP))." (PMID 23577067, 2013). "In contrast, despite the demonstration that MMP-9 serum levels are increased in obesity, its deficiency did not impact on adipogenesis in knockout mice on a high-fat diet." (PMID 23936445, 2013). "Descriptive statistics of all study participant serum samples tested for Bone Panel (osteoprotegrin (OPG), leptin, parathyroid hormone (PTH) and insulin), Matrix Metalloproteinase Panel (MMP-2, MMP-8, MMP-9) and Obesity Panel (adiponectin and C-reactive protein (CRP))." (PMID 23577067, 2013). "Interestingly, the expression of genes involved in low-grade inflammation associated with obesity such as COX-2 (cyclooxygenase 2), CTSS (cathepsin S), and MMP9 (matrix metalloproteinase-9), which are also AhR target genes, was elevated in obese patients." (PMID 21156398, 2011). "The expression of MMP-9 in subcutaneous adipose tissue, a marker of ECM degradation, is higher in metabolically unhealthy obese individuals compared to metabolically healthy lean individuals, suggesting that obesity is more prominently associated with ECM degradation in adipose tissue." (PMID 38562155, 2024). "Thus, MMP9 could be used as a biomarker to identify obesity-related metabolic and cardiovascular problems." (PMID 39594522, 2024).
Obesity (continued). "Hence, MMP9 could play a significant role in the maintenance of the state of chronic low-grade inflammation observed in obesity and commonly referred to as metabolic inflammation or “metaflammation”." (PMID 37445827, 2023). "In children with obesity, MMP-9 genotypes and haplotypes are associated with higher levels of MMP-9, suggesting that genetic factors can alter the relevant pathogenic mechanisms involved in the development of cardiovascular complications associated with obesity in childhood." (PMID 36499740, 2022). "Additionally, MMP9 has been reported to be a marker of obesity." (PMID 35329213, 2022). "However, in the same work, Beales and colleagues demonstrated that adiponectin was able to antagonize leptin effects observed in EAC malignant cells, including MMP-2 and MMP-9 downregulation, thus indicating the importance of hormonal imbalance induced by obesity during EAC genesis and progression." (PMID 32079295, 2020). "Although direct evidence remains limited, preliminary findings suggest that incretin-based pharmacotherapy reduces circulating MMP-2 and MMP-9 levels, highlighting its potential to restore ECM homeostasis and attenuate chronic inflammation in obesity." (PMID 41227041, 2025). "Matrix metalloproteinases (MMPs), especially MMP-2 and MMP-9, are key regulators of ECM remodeling and inflammation in obesity." (PMID 41227041, 2025). "Regarding enzymes, several studies observed significantly higher levels of salivary alpha-amylase (sAA), matrix metalloproteinase-9 (MMP-9), and matrix metalloproteinase-2 (MMP-2) in individuals with obesity, those in the control group." (PMID 40153192, 2025). "Adipocytes contribute to the secretion of proinflammatory cytokines such as TNF-α, IL-1β, MMP-2, MMP-9, IL-6, and MCP-1, as well as adipokines like adiponectin, which further contribute to chronic inflammation in adipose tissue of individuals with obesity." (PMID 38495901, 2024). "The positive correlation of genes such as HSD11B1, PTPN22, ABCC1, MMP9, FGF1, and F13A1 with M0 and M1 macrophages suggests a possible role in shaping the immune response toward a more beneficial phenotype in obesity." (PMID 39594522, 2024). "This showed that obesity is correlated with increased MMP expression in adipose tissue, with MMP-2 and MMP-9 being involved in the ECM remodeling process." (PMID 39766340, 2024). "Metalloproteinases, particularly MMP2, MMP9, and MMP19, regulate the extracellular matrix, which is crucial in multifactorial conditions like obesity and related diseases." (PMID 39683581, 2024). "One can assume that for CRCPs with metabolic syndrome or metabolically healthy obesity, it is the FABP4+MMP9+MMP2-TIMP1- population of circulating sEVs that is the most optimal biomarker reflecting tumor angiogenesis." (PMID 37109070, 2023). "It discovered that adipocytokines and proteases such as CXCL8, MMP9, and C-C Motif Chemokine Receptor 5 (CCR5) were hub genes in white adipose tissue of patients with obesity." (PMID 37886639, 2023). "In summary, this study showed adipocyte secretions under conditions mimicking obesity can instigate cancer progression, activating the FAK cell signaling pathway, stabilizing beta-catenin protein, and increasing MMP-9 expression." (PMID 38068928, 2023). "Our results indicate that in the GSE44000 obesity-related dataset, the expression levels of MNDA, TNC, CHIT1, and MMP9 exhibited significant differences." (PMID 37671970, 2023). "We can assume that for RPC patients with metabolic syndrome or metabolically healthy obesity, the FABP4+MMP9+MMP2-TIMP1- population of plasma sEVs is the most optimal biomarker reflecting tumor angiogenesis." (PMID 37109070, 2023). "The level of both metalloproteinases was significantly higher in patients with a DM2 history longer than 10 years (MMP-3 = 125.7 pg/mL; MMP-9 = 2307.5 pg/mL) and in diabetic patients with obesity (MMP-3 = 128.6 pg/mL; MMP-9 = 2160.9 pg/mL)." (PMID 36362386, 2022).
Obesity (continued). "MMP-9 regulates inflammatory processes by its proteolytic activity and circulating levels of MMP-9 are increased in obesity, metabolic syndrome (MetS) and cardiovascular disease." (PMID 34858196, 2021). "It is also found that obesity reduced AMPK and enhanced YAP and MMP9 expression in the mRNA level by complex effect including an important pathway, the endocrine mechanism." (PMID 33381605, 2020). "Numerous studies demonstrated that ginseng and/or ginsenosides suppressed obesity and adipocyte inflammation by regulating several pathways, such as matrix metalloproteinases (MMP)-2 and MMP-9, AMPK signaling, and/or PPAR-γ signal pathways." (PMID 32630030, 2020). "Protein expression of AMPK and p-AMPK declined significantly (P < 0.05); MMP9, total YAP, and p-YAP protein was significantly upregulated (P < 0.05) in TE-1 cells in the context of obesity." (PMID 33381605, 2020). "In the present study, we showed a higher expression of MMP9 in the cells from the SVF compared to adipocytes in our independent cohort of European men and women with obesity." (PMID 32581226, 2020). "We also detected an increase in the gene expression levels of the ECM-related genes MMP9 and TCN in both groups of patients with obesity compared with normal-weight subjects." (PMID 32283761, 2020). "In obesity, MMP expression is modulated in adipose tissue and MMPs (e.g., MMP-2 and MMP-9) potentially affect adipocyte differentiation." (PMID 26599360, 2015). "Furthermore, we measured significantly increased plasma MMP-9 levels in both the OSAS cohort and the obesity cohort, which positively correlated with BMI and AHI values." (PMID 38172514, 2024). "Obesity may also play a role in the development of airway fibrosis, contributed to by factors such as TGF-β1, MMP-9, and FoxO1." (PMID 38562155, 2024). "We therefore hypothesize that activated MMP-9 and MPO reflect important disease mechanisms in PWS which goes beyond disrupted carbohydrate metabolism and obesity." (PMID 37430349, 2023). "The median concentration of MMP-9 in saliva in our study was the highest in the group of people with obesity and without hepatic steatosis and showed lower values in the groups with a higher degree of steatosis." (PMID 36769216, 2023). "This interesting finding was supported by a previous study that reported a negative correlation between MMP-9 and obesity and muscle strength." (PMID 34458302, 2021). "Even though MMP-9 levels were not affected by obesity status, they are negatively correlated with endothelium-dependent response measured by forearm blood flow." (PMID 34625635, 2021). "While no data on ADAM10 expression or activity in obesity are available, plasma MMP-9 levels and its expression in fat tissue of obese subjects are increased." (PMID 28409494, 2017). "Furthermore, others have shown that some MMPs and their inhibitors (TIMPs) are modulated with obesity level in mice and in humans and that MMP2 and MMP9 are essential for adipocyte differentiation." (PMID 28409151, 2017). "In conclusion, in patients with obesity and type 2 diabetes, insulin infusion leads to a suppression of the expression of IL-4, ADAM-33, LIGHT, and LTBR in parallel with a reduction in plasma NOM, TGFβ, MCP-1, and MMP-9 concentrations." (PMID 25642424, 2015). "Inflammation measured by mRNA expressions of IL-6, MMP-9, PAI-1 and leptin and protein expression of NF-κB was higher, whereas anti-inflammation measured by mRNA expressions of adiponectin and INF-γ was lower in obesity than in control and OR (all p<0.003)." (PMID 22784636, 2012). "Whilst a study examining obesity in adults demonstrated increased MMP-2 (and MMP-9) levels." (PMID 21777433, 2011). "However, we showed that when mice were fed with an HFD and infused with Ang II, the expression of Mmp9 was barely detectable, suggesting that MMP9 is probably not involved in obesity-related AAA progression." (PMID 39872985, 2025).
Obesity (continued). "In the group of patients with coronary artery disease and heart failure burdened with overweight/obesity, a significantly higher transcriptional activity of the metalloproteinase 9 (MMP-9) gene was found in comparison to patients who were not burdened with this risk factor." (PMID 38540214, 2024). "However, except for negative correlation between plasma MMP-9 and total cholesterol there were no other associations between the expression of MMP9/TIMP-1 axis and the obesity phenotype parameters." (PMID 38541059, 2024). "In conclusion, the altered adipokine milieu and metabolites in the context of obesity may promote ESCC growth in vivo; affect proliferation, migration, and invasion of ESCC cells in vitro; and regulate MMP9 and AMPK-YAP signaling pathway through complex effects including the endocrine effect." (PMID 33381605, 2020). "In addition, mice lacking MMP-2, but not MMP9, are also resistant to obesity induced by high-fat diet." (PMID 31627295, 2019). "Finally, we want to know whether obesity could affect MMP3 protein levels and MMP9 activity in lung tumor tissues." (PMID 29137230, 2017). "Importantly, our study subjects did not have obesity and any features of metabolic syndrome which could influence serum MMP-9 concentrations." (PMID 30302090, 2018). "Serum MMP9 levels are increased in patients with NASH and should routinely be measured in patients with obesity, but further investigations are needed to improve noninvasive NASH diagnosis." (PMID 36609276, 2023). "The levels of TRAP, CTSK, RANKL/OPG, matrix metalloproteinase-9 (MMP-9), TRAF6, urinary hydroxyproline, and urinary calcium were increased in the obesity-prone rats after consuming a high-fat diet, which was not seen in the obesity-resistant rats." (PMID 38672518, 2024). "This study is the first to prove that obesity potentiated ESCC growth and invasion with relation to the AMPK-YAP signal pathway and reveal that obesity downregulated AMPK and p-AMPK, while upregulating MMP9, total YAP, p-YAP, and nonphosphorylated YAP protein expression." (PMID 33381605, 2020).